RN7SL326P (RNA, 7SL, cytoplasmic 326, pseudogene)
Gene: Miscellaneous RNA gene on chromosome 1 (40,804,846 to 40,805,141, forward strand). Ensembl gene ENSG00000264582.
Homologues: Orthologues: chimpanzee Metazoa_SRP (99% identical), macaque Metazoa_SRP (92% identical). Paralogues in human: RN7SL2 (87% identical), RN7SL1 (86% identical), RN7SL3 (84% identical), RN7SL45P (84% identical), RN7SL300P (84% identical), RN7SL444P (83% identical), RN7SL147P (83% identical), RN7SL660P (83% identical), RN7SL126P (82% identical), RN7SL357P (82% identical), RN7SL575P (82% identical), RN7SL230P (82% identical), and 705 more.